AKIP1 (A-kinase interacting protein 1)
Diseases named in the same sentence as AKIP1 in open-access papers (continued):
Sharing a sentence is not in itself a finding about the gene and the disease.
metastatic tumours (1 paper, 2020). "mRNA levels of AKIP1 in metastatic tumours were also significantly higher than in metastasis‐free tumours (P < .001)." (PMID 32401379, 2020).
nonsmall-cell lung cancer (1 paper, 2022). "A retrospective study on the nonsmall cell lung cancer patients indicated the expression of AKIP1 was correlated with tumor characteristics and prognosis of these patients." (PMID 35111846, 2022).
papillary thyroid carcinoma (1 paper, 2022). "Importantly, recent research has presented that AKIP1 is correlated with advanced tumor features and higher recurrence risk in papillary thyroid carcinoma." (PMID 35965570, 2022).
cancer (17 papers, 2011 to 2025). A tumor composed of atypical neoplastic, often pleomorphic cells that invade other tissues. "Odds ratios (ORs) with 95% CIs were pooled to estimate the association between AKIP1 expression and clinicopathological characteristics of patients with cancer." (PMID 35758348, 2022). "The cellular role of breast carcinoma-associated protein (BCA3), also known as A-kinase-interacting protein 1 (AKIP-1), is not fully understood." (PMID 29677171, 2018). "AKIP1 expression was negatively associated with overall survival (HR = 1.86, 95% CI: 1.58–2.18, P < .001) and disease-free survival (HR = 1.69, 95% CI: 1.53–1.87, P < .001) in patients with cancer." (PMID 35758348, 2022). "AKIP1 is a small 23 kDa protein originally identified as a breast cancer associated gene (BCA3)." (PMID 30181740, 2018). "A Kinase-Interacting Protein 1: Initially identified as breast cancer-associated gene 3 (BCA3), A Kinase-Interacting Protein 1 (AKIP1) exhibits upregulation in various cancer types and is also present in most normal tissues." (PMID 40869079, 2025). "A cumulative meta-analysis was conducted to evaluate the prognostic value of AKIP1 in human cancers." (PMID 35758348, 2022). "Although the prognostic value of AKIP1 has been studied in various cancers it remains controversial." (PMID 35758348, 2022). "We attempted to better clarify the prognostic value of AKIP1 expression for OS by conducting subgroup analyses, according to cancer type, clinical stage, detection method, sample size, and analytical method." (PMID 35758348, 2022). "Here, we conducted a meta-analysis to evaluate the prognostic value of AKIP1 expression in patients with cancer." (PMID 35758348, 2022). "Our study indicated that high AKIP1 expression was negatively associated with OS and DFS in patients with cancer." (PMID 35758348, 2022). "For instance, AKIP1 is upregulated in several cancers, and it also correlates with more deteriorative tumor features and survival profiles in these cancer patients, which suggests that it participates in the progression of many cancers." (PMID 35355804, 2021). "These all indicate that AKIP1 acts as a promotor in the development of cancers, which is in consistence to our results." (PMID 35355804, 2021). "AKIP1 expression in the samples of CC patients and in in vitro tumour cell lines provides evidence that expression of AKIP1 in CC contributes to cancer progression." (PMID 32401379, 2020). "Consistent with previous reports, this study found that the metastasis of cancer cells was promoted by AKIP1 via the EMT, which was regulated by the NF‐κB pathway." (PMID 32401379, 2020). "A‐kinase‐interacting protein 1 (AKIP1) has previously been reported to act as a potential oncogenic protein in various cancers." (PMID 31020809, 2019). "AKIP1 has been shown to localize to mitochondria in both cancer cells and cardiomyocytes, but its functional role in mitochondria is still elusive." (PMID 24236204, 2013). "AKIP1 has been mostly investigated in cancer cells, but recently its role in cardiac tissue has gained interest." (PMID 24169435, 2013). "This is particularly true for cancer cell lines, in which AKIP1 has been primarily investigated and in which it was originally identified as a breast cancer expressed gene." (PMID 24169435, 2013). "One paper suggested that the level of AKIP1 plays a determining role in either the activation or inhibition of p65 resulting in cell proliferation or cell death in cancer cell lines." (PMID 21556136, 2011). "The inhibition of apoptosis in porcine AKIP1-TG cells, as demonstrated by reduced caspase-3 and caspase-7 activity following oxidative stress, confirms findings from earlier studies of cardiomyocytes and cancer models." (PMID 40869079, 2025). "Previous studies have reported AKIP1 upregulation in various cancers." (PMID 40869079, 2025). "In cancer cells, AKIP1 influences NF-κB and Protein Kinase A (PKA) activity." (PMID 40869079, 2025).
cancer (continued). "AKIP1 expression may prove to be an effective prognostic marker, and AKIP1 may be a promising target for treatment of patients with cancer." (PMID 35758348, 2022). "Meta-analysis of AKIP1 and clinicopathological features in cancer patients." (PMID 35758348, 2022). "High AKIP1 expression is an unfavorable prognostic biomarker and may serve as a potential therapeutic target in patients with cancer." (PMID 35758348, 2022). "AKIP1 has been extensively found to serve as an oncogenic regulator that can facilitate growth and metastasis of several tumors via activation of signaling pathways, thereby affecting the progression of various cancers." (PMID 35111846, 2022). "Besides, AKIP1 expression is elevated in both tumour cells and in the plasma in many types of cancer, including CC." (PMID 32401379, 2020). "In cancer cell lines a role for AKIP1 in nuclear-cytoplasmic shuttling of PKA and NFκB has been proposed, but AKIP1 may also be involved in apoptosis." (PMID 24236204, 2013). "Moreover, AKIP1 is proposed to modulate chemoresistance in several cancers." (PMID 35965570, 2022). "In addition, these results lend credence to the mediating role of AKIP1 in cancer progression." (PMID 31945087, 2020). "Surprisingly, AKIP1′s protective role in I/R injury cannot be solely attributed to its interactions with signaling molecules like NF-κB, PKA, or AKT, as observed in cancer." (PMID 40869079, 2025). "As recently shown in several cancer cell lines, accessory proteins such as AKIP1 control the PKA-induced activation of NF-κB, allowing the precise prediction of the impact of PKA inhibition as a cancer treatment." (PMID 35805104, 2022). "However, the prognostic value of AKIP1 expression in various cancers remains unclear." (PMID 35758348, 2022). "Subgroup analysis demonstrated that high AKIP1 expression was a predictor of poor OS, independent of cancer type, clinical stage, detection method, sample size, and analytical method." (PMID 35758348, 2022). "Since AKIP1 localizes to the nucleus and has been shown to modulate transcription via NFκB and SIRT1 in cancer cell lines, the mitochondrial changes may be a result of altered transcription of nuclear encoded mitochondrial genes." (PMID 24236204, 2013). "AKIP1 has been mainly studied in cancer cell lines, but is also expressed in many normal, non-tumor, cells in different organs." (PMID 24236204, 2013). "Recently, it was shown that in different cancer cell lines, the PKA-induced activation of NF-kappa-B is determined by accessory proteins like the A-kinase-interacting protein 1, so that the effect of PKA inhibition for anti-cancer therapy can be precisely predicted." (PMID 24212646, 2011). "However, based on our current understanding, we believe this upregulation likely reflects a protective response by cancer cells to oxidative stress and a mechanism to support their high energy demands rather than a direct oncogenic role of AKIP1 itself." (PMID 40869079, 2025).
tumor (15 papers, 2013 to 2026). "The clinical association analysis revealed overexpression of AKIP1 was positively correlated with tumour size, clinical metastasis, and a shorter OS time of GC patients, thus proving its crucial role in GC evolution and metastasis." (PMID 31020809, 2019). "Another interesting study discloses that AKIP1 activates Zinc Finger E-Box Binding Homeobox 1 (ZEB1) to facilitate tumor metastasis in non-small cell lung cancer." (PMID 35965570, 2022). "Cumulative evidence suggests that A-kinase interacting protein 1 (AKIP1) plays an important role in tumor progression." (PMID 35758348, 2022). "The results revealed that high AKIP1 expression was positively correlated with tumor size, clinical stage, depth of tumor invasion, and degree of lymph node metastasis." (PMID 35758348, 2022). "To make a further verification of the role of AKIP1 in vivo, we established subcutaneous xenograft tumour and lung metastasis model in nude mice." (PMID 31020809, 2019). "In this study, we demonstrated that AKIP1 was highly expressed in GC tissues compared with that in their non‐tumour counterparts." (PMID 31020809, 2019). "Since AKIP1 has been shown to interact with PKA in tumor cells, AKIP1 co-immunoprecipitation was performed followed by western blot analysis of PKA." (PMID 24169435, 2013). "Therefore, inhibiting AKIP1 was found to have anti-tumor effects via the inhibition of its interaction with PKA." (PMID 38893192, 2024). "Recently, it has been reported that AKIP1 is viewed as a tumor promoter." (PMID 35965570, 2022). "Besides, the IHC analysis of 96 cases further revealed that AKIP1 expression was markedly elevated in tumour tissues compared with that in corresponding normal tissues, especially in metastatic tumour tissues." (PMID 31020809, 2019). "AKIP1 is responsible for interacting with protein kinase A (PKA), an enzyme that plays a key role in cellular signaling pathways promoting tumor progression." (PMID 38893192, 2024). "After 30 days, MKN45 sh‐NC cell‐derived tumours at the subcutaneous implantation sites were larger and grew more rapidly than MKN45 sh‐AKIP1 cell‐derived tumours." (PMID 31020809, 2019). "AKIP1 is a positive regulator of EMT in CC cells, suggesting that the EMT pathway could become a target to prevent tumour metastasis." (PMID 32401379, 2020).
infection (2 papers, 2021 to 2022). The state of being infected such as from the introduction of a foreign agent such as serum, vaccine, antigenic substance or organism. "As expected, TM levels were significantly increased in WT mice but not in Akip1−/− littermates by Ad-VP35 (not by Ad-null) infection." (PMID 35474062, 2022).
cardiovascular diseases (1 paper, 2025). "Testing pharmacological strategies to upregulate AKIP1 or deliver AKIP1 mimetics in disease models could offer promising avenues for treating oxidative-stress-related conditions, such as cardiovascular diseases, neurodegenerative disorders, and organ damage from ischemia–reperfusion injury." (PMID 40869079, 2025).
AKIP1 also shares sentences with these, for which no sentence is quoted: non-small cell lung carcinoma (3 papers); clear cell renal cell carcinoma (1); colorectal cancer (1); digestive system cancer (1); glioblastoma (1); head and neck cancer (1); HIV-1 infection (1); hypertrophy (1); lung adenocarcinoma (1); malignant glioma (1); multiple myeloma (1); thyroid carcinoma (1).